HPX (hemopexin)
Diseases named in the same sentence as HPX in open-access papers (continued):
Sharing a sentence is not in itself a finding about the gene and the disease.
Hepatic hemangioma (1 paper, 2025). A congenital vascular malformation in the liver composed of masses of blood vessels that are atypical or irregular in arrangement and size. "Then, mice with orthotopic liver hemangioma were divided into four groups: sham, RFA, RFA + glycyrrhizin, and RFA + hemopexin." (PMID 41280917, 2025). "In addition, hemopexin and glycyrrhizin were used to investigate the impact of HMGB1 on heme-induced SIRS post-RFA in hepatic hemangioma mice." (PMID 41280917, 2025). "Collectively, these findings indicate that hemopexin and glycyrrhizin may be the potential strategies for further study for SIRS following RFA of hepatic hemangioma." (PMID 41280917, 2025). "In addition, our study indicates that hemopexin, a heme scavenger, and glycyrrhizin, a HMGB1 inhibitor, could alleviate SIRS after RFA of hepatic hemangioma." (PMID 41280917, 2025).
idiopathic nephrotic syndrome (1 paper, 2021). Nephrotic syndrome for which no cause has been identified. "Hemopexin (Hpx) is considered a factor in the pathogenesis of idiopathic nephrotic syndrome (INS)." (PMID 34300326, 2021).
influenza infection (1 paper, 2021). "These selected proteins, such as plasma protease C1 inhibitor, hemopexin, transferrin, complement factor B and complement C3, have been identified as candidate biomarkers of acute respiratory virus infection or exhibited obvious fold changes during influenza infection." (PMID 34867309, 2021).
iron deficiency (1 paper, 2015). "Notably, it was reported that iron deficiency induces TF receptor expression and doubles the number of HPX surface receptors (subsequently increasing HPX-mediated heme uptake in vitro)." (PMID 25656928, 2015).
liver cirrhosis (1 paper, 2015). "Patients with compromised liver function, especially liver cirrhosis and a history of alcohol abuse will not readily synthesize HPX, transferrin and Hp—all extracellular anti-oxidants against heme and iron." (PMID 26175690, 2015).
lymph node metastasis (1 paper, 2020). "Expression scores of hemopexin in cases with lymph node metastasis were 0 in 21, 1 in 37, 2 in 54 and 3 in 16 cases (N1; 0 in 18, 1 in 28, 2 in 36 and 3 in 8 cases, N2; 0 in 2, 1 in 10, 2 in 18 and 3 in 8 cases)." (PMID 32663208, 2020).
memory impairment (1 paper, 2023). "Therefore, the onset of memory impairment occurred earlier in mice with skeletal muscle atrophy, and this was due to the effects of hemopexin on the brain secreted by atrophied muscles." (PMID 37554940, 2023).
meningioma (1 paper, 2014). A generally slow growing tumor attached to the dura mater. "Compared to the healthy controls, all the three grades of meningioma patients found to have higher serum level of Apo E and HPX (p < 0.01 in a Mann-Whitney test)." (PMID 25413266, 2014). "ROC curve analysis demonstrated apolipoprotein E and A-I and hemopexin as efficient predictors for meningiomas." (PMID 25413266, 2014). "Receiver operating characteristic (ROC) curve analysis was carried out to evaluate the individual performance of 4 proteins; HPX, Apo E and A-I, RBP4 for prediction of different grades of meningiomas." (PMID 25413266, 2014). "Hemopexin (HPX), apolipoprotein E and A-I (Apo E and A-I), and plasma retinol binding protein (RBP4) concentrations were directly measured in the serum samples of healthy controls and meningiomas patients (MGI, MGII and MGIII) using ELISA." (PMID 25413266, 2014).
Miscarriage (1 paper, 2025). A pregnancy that ends at a stage in which the fetus is incapable of surviving on its own, defined as the spontaneous loss of a fetus before the 22th week of pregnancy. "Both melanotransferrin (MELTF) and hemopexin (HPX) are involved in heme and iron metabolism with abnormal expression correlated with miscarriage." (PMID 40430124, 2025).
multiple sclerosis (1 paper, 2021). A progressive autoimmune disorder affecting the central nervous system resulting in demyelination. "Cerebrospinal fluid levels of legumain, C1q and hemopexin were not significantly different between multiple sclerosis patients, other neurological diseases, or healthy controls." (PMID 33785790, 2021).
myocarditis (1 paper, 2026). Myocarditis is a condition that is characterized by inflammation of the heart muscle (myocardium). "Importantly, quantitative proteomics and molecular docking revealed hemopexin (Hpx) as the potential therapeutic target of crocins in ICI-related myocarditis." (PMID 41596558, 2026).
myopia (1 paper, 2021). "Two of these myopia-specific exosomal proteins, TTR and HPX have been found in previous myopia associated research." (PMID 33850473, 2021).
neuroblastoma (1 paper, 2017). Neuroblastoma (NB) is the most common solid, extracranial childhood tumor. "Among them, two N-linked glycoproteins, alpha-2-HS-glycoprotein (AHSG) and hemopexin (HPX), markedly exhibited the WN1316-mediated cytoprotection against oxidative injury in differentiated neuroblastoma SH-SY5Y cells." (PMID 29016670, 2017).
neuropathy (1 paper, 2022). A disorder affecting the nervous system that manifests with pain, tingling, numbness, and/or muscle weakness. "Anti-hemolysis therapies, such as heme-chelating recombinant hemopexin or EV-neutralizing annexin-A5 may also be tested to treat T2D patients with low-grade IVH or established neuropathy." (PMID 36251660, 2022).
pancreatic (1 paper, 2020). "This view was bolstered by the results of in vitro assays showing that hemopexin strongly promoted the invasive ability of the pancreatic-cancer cells." (PMID 32663208, 2020).
periodontitis (1 paper, 2022). An acute or chronic inflammatory process that affects the tissues that surround and support the teeth. "Therefore, in the context of the present study, the increase of HPX could be considered a protective strategy as opposed to the oxidative stress condition and inflammation associated with severe periodontitis." (PMID 35329612, 2022).
pneumonia (1 paper, 2018). An acute, acute and chronic, or chronic inflammation focally or diffusely affecting the lung parenchyma, caused by an infection in one or both of the lungs (by bacteria, viruses, fungi, or mycoplasma.). "We provide evidence that large volume resuscitation with stored blood, compared to fresh blood, in mice increases mortality from subsequent pneumonia, which occurs via mechanisms sensitive to hemopexin and TLR4 and HMGB1 inhibition." (PMID 29522519, 2018).
porphyria (1 paper, 2025). Porphyria is a group of diseases in which substances called porphyrins build up, negatively affecting the skin or nervous system. "However, considering the etiology of the pathology (hemolytic disorders, parasite invasion, gastric problems, or porphyria treatment), the plasma scavenging system (haptoglobin, hemopexin, and albumin) would be challenged either by the overwhelming formation of hemin and hematin." (PMID 39996728, 2025).
primary Sjögren’s syndrome (1 paper, 2023). "A previous explorative proteomic study in patients with primary Sjögren’s syndrome associated CSF HPX and PEDF concentrations with fatigue." (PMID 37365509, 2023).
rheumatoid arthritis (1 paper, 2014). A chronic, systemic autoimmune disorder characterized by inflammation in the synovial membranes and articular surfaces. "Ficolin 3, Haptoglobin, Alpha-1-antitrypsin, Hemopexin precursor and IgM chain also showed increased expression in plasma of rheumatoid arthritis patients as an indication of immune response." (PMID 25350754, 2014).
sarcopenia (1 paper, 2025). Progressive decline in muscle mass due to aging which results in decreased functional capacity of muscles. "Proteomic set enrichment analysis revealed enrichment of several pathways related to sarcopenia, such as hemopexin, defence response and cell differentiation, in sarcopenia group." (PMID 40207397, 2025).
scurvy (1 paper, 2013). A condition that develops in people who do not consume an adequate amount of vitamin C in their diet. "When the antioxidant capacity of Hp is insufficient, its role is taken over by hemopexin and vitamin C. The relative number of scurvy victims corresponds with the Hp 2-2 frequency, which is associated with iron conservation and has an impact on vitamin C stability." (PMID 24036531, 2013).
uveal melanoma (1 paper, 2014). A melanoma derived from melanocytes of the uveal tract. "In metastases of uveal melanomas, several proteins were found to be upregulated: Colony stimulating factor 2, Ficolin precursor, Haptoglobin -2 precursor, Hemopexin precursor, α-1-antitrypsin precursor, α-1-antichymotrypsin precursor, Vitronectin precursor, and Down syndrome cell adhesion molecule." (PMID 24392146, 2014).
Venous thrombosis (1 paper, 2023). Formation of a blood clot (thrombus) inside a vein, causing the obstruction of blood flow. "Furthermore, in HPX-null mice with venous thrombosis induced by ligation of the inferior vena cava (IVCL), the clot size and weight were substantially greater than those in wild-type IVCL mice, underscoring the protective role of HPX in venous thrombosis." (PMID 38022615, 2023).
infection (29 papers, 2012 to 2025). The state of being infected such as from the introduction of a foreign agent such as serum, vaccine, antigenic substance or organism. "On day 3 of infection, both wild-type and hemopexin-deficient mice displayed growth of fungal hyphae in the lung, associated with areas of leukocyte infiltration and lung injury." (PMID 40232861, 2025). "The extent of lung injury, as seen on histology, was more severe in hemopexin-deficient than wild-type mice in the context of infection." (PMID 40232861, 2025). "To further quantify the extent of lung injury, we measured BAL albumin and found that hemopexin-deficient animals had normal lung barrier integrity at baseline but increased permeability during the infection." (PMID 40232861, 2025). "The model does not explicitly include hemopexin; instead, we vary the heme quantity in the alveoli to reproduce the amounts of heme observed in wild-type and hemopexin-deficient mice during the infection." (PMID 40232861, 2025). "These patterns support the interpretation that HPX functions as a developmentally regulated oxidative buffer—not limited to hemolysis or infection but integrated into the broader physiological adaptations required during early life-stage transitions." (PMID 40869255, 2025). "Hemopexin (Hx) is another acute phase protein that, along with Hp, is induced during infection and after inflammation to minimize tissue damage and facilitate tissue repair." (PMID 34576090, 2021). "Hemopexin is an acute phase protein that responds in activation to trauma, infection, stress, or inflammation." (PMID 34583348, 2021). "Haptoglobulin and hemopexin in the 15th and 20th days after infection level, 60 days after infection by the statistically significant higher levels indicate that continued efforts be eliminated of intracellular pathogens." (PMID 32257894, 2019). "Hepatic levels of HPX and Hp mRNA rose after infection in WT mice and in the IL22−/− mice, but to a significantly lesser extent; consequently, Hb accumulated in the plasma due to the ongoing hemolysis caused by the infection." (PMID 31554244, 2019). "After infection 10th, 15th and 20th day groups, compared to control group of anti-inflammatory effects that stands out with haptoglobulin and hemopexin levels statistically higher (p < 0.05) even in these days,shows inflammatory process continued." (PMID 32257894, 2019). "More than the maximum number of tissue cysts after infection 30, 45 and 60 days showed a decrease in the concentration of Haptoglobulin and hemopexin." (PMID 32257894, 2019). "All eight were also identified as up-regulated in infection by Orbitrap (100% probability) and all but hemopexin were reflected in corresponding SELDI peaks (±5% mass range) when the SELDI database was queried." (PMID 27138990, 2016). "Infection by SARS-CoV-2 virus may require higher levels of HPX to scavenge and reduce the toxic effects of free heme." (PMID 41369364, 2025). "This could explain why HO-1-deficient mice are highly vulnerable to immune-mediated inflammatory diseases, even when in the presence of hemopexin, including polymicrobial infection or during a beneficial stress, such as exercise training." (PMID 37237940, 2023). "recovered significantly higher bacterial loads from the bronchoalveolar lavage fluid samples of mice that had been administered heme prior to infection, whilst impaired bacterial clearance was reported in hemopexin knockout mice challenged with S.aureus following a liver crush injury." (PMID 37662933, 2023). "The conclusion that iron availability is important for Mtb during infection is also supported by the observation that high concentrations of transferrin, haptoglobin, and hemopexin are present in the necrotic centers of lung granulomas, the primary sites of infection in human TB patients." (PMID 31534126, 2019).
infection (continued). "In this study it is found that, serum amyloid A, haptoglobulin, hemopexin, α-macroglobulin and clusterin have been identified as major acute phase proteins and was found to quickly peaked in the first 10-day period after infection Toxoplasma gondii infection induced in mice." (PMID 32257894, 2019). "Increased expression of several acute-phase reactants, such as amyloid A proteins (Saa1, Saa2, Saa3), amyloid P component serum (Apcs), haptoglobin (Hp), hemopexin (Hpx) and orosomucoid 2 (Orm2), was observed only in CerS2-null mice after transfer of iNKT cells and infection with LCMV." (PMID 29163475, 2017). "In addition, the fact that hemopexin levels increased rapidly in both groups of P. c. adami-infected mice implies effective scavenging of free HE concurrent to hemolysis in this mouse infection model." (PMID 26465787, 2015). "Moreover, no study to our knowledge has examined whether a relationship exists between circulating levels of heme, hemopexin and/or haptoglobin, and the development of infections in hospitalised trauma patients." (PMID 37662933, 2023). "The major acute phase proteins Alpha-1 antitrypsin (A1AT) members 1 and 3, Haptoglobin, Hemopexin, Alpha-1 acid glycoprotein, CRP, and SAA2 reached comparable maximum fold change values at the common post-infection time-points between the infection types." (PMID 30774579, 2019). "For HPX, CP and RBP4 differential abundance was observed only in the FEB stage of the infection, while alterations in their serum abundances during the DEF and CON stages were found to be statistically insignificant (p > 0.05)." (PMID 28667326, 2017). "Hemopexin (HPX) is a vertebrate-specific glycoprotein that binds free heme with high affinity, playing a crucial role in heme detoxification, iron homeostasis, and inflammation modulation during infection and tissue injury." (PMID 40869255, 2025). "HPX has recently been linked to host immunity and the anti-microbial action of IL-22 because, in mice, limiting infection depends upon HPX but not on Hp, in spite of the fact that the expression of both proteins in the liver is induced by IL-22." (PMID 31554244, 2019). "Evidence supports that HPX is protective in both the presence and absence of bacterial/pathogen infection." (PMID 31554244, 2019). "Examples from patients and experimental animals provide evidence that HPX and Hp act simultaneously in various niches of the body when hemolysis occurs, both in the presence or absence of infection and inflammation." (PMID 26175690, 2015). "Interestingly, the set of data [EPO + hemopexin + total heme] correlated significantly to [TNF-α + IL-10 + IP-10 + MCP-1] during infection, and more specifically for the CM, and NCM groups, but not for MM patients." (PMID 27441662, 2016). "Intriguingly, when the patient developed an infection (pharyngitis, fever and strep throat) there was a rapid and marked two-fold increase in Hp levels within 2–4 days without significant changes in HPX plasma levels, demonstrating that it is not an acute phase protein in humans." (PMID 26175690, 2015).
cancer (21 papers, 2006 to 2025). A tumor composed of atypical neoplastic, often pleomorphic cells that invade other tissues. "Hemopexin has been linked to various cancers and approximately half of deaths of cancer patients with malignant tumors are associated with thrombotic events." (PMID 31554244, 2019). "This led to the speculation that low levels of HPX might allow more iron to directly enter cancer cells, potentially causing ferroptosis and resulting in a favorable prognosis for patients with CRC60." (PMID 38321225, 2024). "In addition, overexpression of hemopexin activates the tumor-associated matrix metalloproteinases (MMPs), enzymes that promote tumor progression by facilitating cancer invasion and metastasis." (PMID 32663208, 2020). "In this study, through pan-cancer analysis, we found that HPX is lowly expressed in HCC and negatively correlated with poor prognosis." (PMID 41008813, 2025). "In contrast, previous studies on HPX have mainly focused on its role as a scavenger of labile heme in the tumor microenvironment, where it suppresses cancer progression by limiting heme-induced oncogene activation, such as c-MYC." (PMID 41008813, 2025). "This study systematically investigated the role of fibrinolysis in pan-cancer; we successfully identified the fibrinolysis-related gene HPX influencing HCC progression." (PMID 41008813, 2025). "HPX, traditionally known for its role in heme scavenging, has emerging evidence linking it to cancer progression." (PMID 41008813, 2025). "Proteomic profiling of C26 cancer cachexia mice gastrocnemius show an increased expression of a hemopexin precursor." (PMID 38022578, 2023). "Considering the emerging importance of heme in tumors, the present review proposes an update of the works investigating hemopexin involvement in cancer, with the attempt to stimulate further future studies on this topic." (PMID 35055182, 2022). "We postulated that hemopexin present in the stroma of PDAC binds to LRP1 on the cancer-cell membrane, thereby promoting invasion by activating the mitogen-activated protein-kinase pathway and the NF-κβ pathway." (PMID 32663208, 2020). "Hemopexin was expressed in the cancer-cell cytoplasm and in stromal fibroblasts (B), FTL expression was localized in the same location as hemopexin (not shown here)." (PMID 32663208, 2020). "GREAT also reported that HepG2-enriched windows were close to many cancer genes HPX, HPN, LCAT, TST, GSTM1, CEPBA, CYP2B6." (PMID 25522020, 2014). "However, a recent study also showed that hemopexin suppresses cancer cell dissemination by sequestering heme in the TME." (PMID 40628700, 2025). "Hemopexin has recently been gained attention for promoting cancer progression and metastasis." (PMID 40628700, 2025). "There are several studies of cancer cachexia models that demonstrate a relationship to hemopexin." (PMID 38022578, 2023). "However, immunohistochemistry revealed strong hemopexin expression in not only fibroblasts but also cancer-cell cytoplasm." (PMID 32663208, 2020). "Hemopexin may have paracrine and autocrine mechanisms with crosstalk of cancer cells and CAF." (PMID 32663208, 2020). "Thus, hemopexin production potentially by cancer cells should be considered, and whether hemopexin affects CAF or other tumor-microenvironment components should be investigated." (PMID 32663208, 2020). "These include: CDH1, MUC1, THBS4, and MSLN for PEs related to cancer; ADA2, CXCL10, and WARS for TB-PEs; CRP, S100A9, and VIM for parapneumonic PEs; and C9, LDHA, HPX, LDHB, and C3 for benign-PEs." (PMID 35197508, 2022). "APOC3, APOH, HPX, and FGB expression levels were highest in HCC and were greater in normal tissues than that in cancer tissues." (PMID 35449866, 2022). "Targeting HPX with a small inhibitor can selectively inhibit MT1-MMP activity and suppress cancer cell growth." (PMID 36093157, 2022). "The expression levels of APOC3, APOH, HPX, and FGB were the highest in HCC and were higher in normal tissues than in cancer tissues." (PMID 35449866, 2022).